S100A12 (S100 calcium binding protein A12)
Diseases named in the same sentence as S100A12 in open-access papers (continued):
Sharing a sentence is not in itself a finding about the gene and the disease.
S100A12 also shares sentences with these, for which no sentence is quoted: systemic lupus erythematosus (5 papers); Acute otitis media (3); gastrointestinal disease (3); gingivitis (3); Hypertension (3); interstitial lung disease (3); Obesity (3); adenocarcinoma (2); Airway obstruction (2); amyloidosis (2); arthropathy (2); atopic dermatitis (2); autoimmune disorders (2); benign tumors (2); Blau syndrome (2); chronic periodontitis (2); Cirrhosis (2); dementia (2); Diarrhea (2); Hypoalbuminemia (2); lymphopenia (2); Protein-losing enteropathy (2); schizophrenia (2); allergic asthma (1); and large cell carcinomas (1); ankylosing spondylitis (1); Anorexia (1); astrocytoma (1); atrophic gastritis (1); autoimmune pancreatitis (1).
A further 91 diseases each share a sentence with S100A12 in 1 paper.